GTF2IRD2B (GTF2I repeat domain containing 2B)
Synonyms: GTF2IRD2; GTF2IRD2A
Tractability: PROTAC: ubiquitination databases record sites on it.
Gene: Protein-coding gene on chromosome 7 (75,092,396 to 75,149,818, forward strand). Ensembl gene ENSG00000174428.
Subcellular location: Nucleus
Subcellular location (Human Protein Atlas): Nucleoplasm
Gene Ontology:
Molecular function: protein binding; DNA-binding transcription factor activity, RNA polymerase II-specific
Biological process: regulation of transcription by RNA polymerase II
Cellular component: nucleoplasm; nucleus
Genetic constraint (gnomAD): Loss-of-function variants: 6 observed, 13.62 expected, observed/expected ratio (o/e) 0.44, 90% interval 0.24 to 0.87. The synonymous counts are far from expectation, so gnomAD's model fits this gene poorly and the ratio says little. Missense variants: 98 observed, 244.48 expected, observed/expected ratio (o/e) 0.4, 90% interval 0.34 to 0.47. Synonymous variants: 49 observed, 86.54 expected, observed/expected ratio (o/e) 0.57, 90% interval 0.45 to 0.72.
Homologues: Orthologues: rat Gtf2ird2 (80% identical), mouse Gtf2ird2 (79% identical). Paralogues in human: GTF2IRD2 (99% identical), GTF2I (36% identical), GTF2IRD1 (20% identical), ZMYM4 (7% identical), ZMYM3 (7% identical), ZMYM2 (6% identical), THAP12 (6% identical), ZMYM1 (6% identical), ZMYM6 (5% identical), QRICH1 (5% identical), KIAA1958 (4% identical), SCAND3 (4% identical), and 6 more.
Diseases named in the same sentence as GTF2IRD2B in open-access papers:
GTF2IRD2B is named in the same sentence as 5 diseases in open-access papers, as found by Europe PMC text mining. Sharing a sentence is not in itself a finding about the gene and the disease. The quoted sentences say what the papers report.
hepatocellular carcinoma (1 paper, 2024). A malignant tumor that arises from hepatocytes.
cardiovascular disease (1 paper, 2020). "As an example for the overlap between lung-related GWAS traits and eQTL in PAH, the novel GTF2IRD2B cis-eQTL rs13238996 overlaps with multiple phenotypes including COPD, lung function, cardiovascular disease and diastolic blood pressure." (PMID 33105808, 2020).
GTF2IRD2B also shares sentences with these, for which no sentence is quoted: supravalvular aortic stenosis (1 paper); tumor (1); Williams-Beuren syndrome (1).